KCNB2 (potassium voltage-gated channel subfamily B member 2)
Description:
Voltage-gated potassium channel that mediates transmembrane potassium transport in excitable membranes, primarily in the brain and smooth muscle cells. Channels open or close in response to the voltage difference across the membrane, letting potassium ions pass in accordance with their electrochemical gradient. Homotetrameric channels mediate a delayed-rectifier voltage-dependent outward potassium current that display rapid activation and slow inactivation in response to membrane depolarization. Can also form functional heterotetrameric channels with other alpha subunits that are non-conducting when expressed alone, such as KCNS1 and KCNS2, creating a functionally diverse range of channel complexes. In vivo, membranes probably contain a mixture of heteromeric potassium channel complexes, making it difficult to assign currents observed in intact tissues to any particular potassium channel family member. Contributes to the delayed-rectifier voltage-gated potassium current in cortical pyramidal neurons and smooth muscle cells.
Synonyms: Kv2.2
Tractability: Small molecule: an approved drug acts on it; it belongs to a druggable protein family. Antibody: its Gene Ontology location is reachable by antibodies, with high confidence; UniProt places it where antibodies can reach, with medium confidence; UniProt predicts a signal peptide or a membrane-spanning region; the Human Protein Atlas places it where antibodies can reach. PROTAC: ubiquitination databases record sites on it; its protein half-life has been measured; a small molecule that binds it is known.
Target class: Potassium channels; Ion channel; Voltage-gated ion channel; Voltage-gated potassium channel
Gene: Protein-coding gene on chromosome 8 (72,537,225 to 72,938,349, forward strand). Ensembl gene ENSG00000182674.
Subcellular location: Cell membrane; Perikaryon; Cell projection, dendrite
Subcellular location (Human Protein Atlas): Plasma membrane; Midbody; Nucleoli
Pathways (Reactome):
Neuronal System: Voltage gated Potassium channels
Gene Ontology:
Molecular function: protein binding; delayed rectifier potassium channel activity; potassium channel regulator activity; protein heterodimerization activity; monoatomic ion channel activity; voltage-gated potassium channel activity
Biological process: action potential; potassium ion transmembrane transport; potassium ion transport; protein localization to plasma membrane; regulation of smooth muscle contraction; monoatomic ion transport; protein homooligomerization; transmembrane transport
Cellular component: dendrite; membrane; neuronal cell body; neuronal cell body membrane; perikaryon; plasma membrane; voltage-gated potassium channel complex
Genetic constraint (gnomAD): Loss-of-function variants: 15 observed, 65.18 expected, observed/expected ratio (o/e) 0.23, 90% interval 0.15 to 0.35. The upper end of that interval is the gene's LOEUF score, 0.35, which puts it in group 1 of 6, group 1 being the genes least tolerant of losing a copy. Missense variants: 821 observed, 1,181.6 expected, observed/expected ratio (o/e) 0.69, 90% interval 0.65 to 0.74. Synonymous variants: 457 observed, 473.96 expected, observed/expected ratio (o/e) 0.96, 90% interval 0.89 to 1.04.
Homologues: Orthologues: chimpanzee KCNB2 (99% identical), macaque KCNB2 (99% identical), guinea pig KCNB2 (95% identical), dog KCNB2 (94% identical), rabbit KCNB2 (94% identical), pig KCNB2 (93% identical), tropical clawed frog kcnb2 (74% identical), zebrafish kcnb2b (57% identical). Paralogues in human: KCNV1 (23% identical), KCNS3 (22% identical), KCND1 (22% identical), KCNC3 (21% identical), KCNS2 (21% identical), KCND2 (21% identical), KCNF1 (21% identical), KCNC2 (21% identical), KCND3 (21% identical), KCNC4 (21% identical), KCNG1 (21% identical), and 19 more.
Diseases named in the same sentence as KCNB2 in open-access papers:
KCNB2 is named in the same sentence as 25 diseases in open-access papers, as found by Europe PMC text mining. Sharing a sentence is not in itself a finding about the gene and the disease. The quoted sentences say what the papers report.
breast carcinoma (2 papers, 2022 to 2025). "The study also identified 22 unique ion channels in the metastatic state, of which GRIK2, GJB3, KCNB2, KCNA1 and KCNK2 were previously reported in breast cancer metastasis." (PMID 35326596, 2022).
epilepsy (2 papers, 2021 to 2024). A brain disorder characterized by episodes of abnormally increased neuronal discharge resulting in transient episodes of sensory or motor neurological dysfunction, or psychic dysfunction. "Additionally, a number of VGKCs including KCNB2, KCNF1, KCNK6, KCNK9 and KCNJ5 are significantly upregulated in the NRXN1α+/- transcriptome, and gain of function of VGKCs has been identified in neurodevelopmental disorders including epilepsy." (PMID 34525970, 2021).
migraine (2 papers, 2011 to 2012). "Cardiac left ventricular systolic dimensions and the common migraine is associated to a region that includes KCNB2." (PMID 22412388, 2012).
co-infection (1 paper, 2013). "The co-infection of HEK293T cells with miR-1 and the 3’UTRs of KCNE1/KCNB2 plasmids resulted in lower luciferase activity compared with infection with the plasmid alone." (PMID 24386485, 2013).
colon tumor (1 paper, 2024). "Other regulators for colon tumor differentiation were identified such as Styl2, Kcnb2, Nrg1, and Mpp5." (PMID 38893159, 2024).
hidradenitis suppurativa (1 paper, 2025). A chronic suppurative and cicatricial disease of the apocrine glands occurring chiefly in the axillae in women and in the groin and anal regions in men. "Potassium channels: Pain perception in hidradenitis suppurativa may be significantly influenced by the dysregulation of potassium channels, including genes such as KCNMA1, KCNQ5, KCNB2, KCND2, KCND3, and KCNAB3, all of which were identified in this study." (PMID 39940809, 2025).
osteoarthritis (1 paper, 2019). A noninflammatory degenerative joint disease occurring chiefly in older persons, characterized by degeneration of the articular cartilage, hypertrophy of bone at the margins and changes in the synovial membrane. "CCDC85C and KCNB2 have both previously been found to be altered in screening for biomarkers with significantly higher levels in RA patients compared with healthy controls and osteoarthritis (OA) patients, respectively." (PMID 31842970, 2019).
viral infection (1 paper, 2013). "First, KCNE1 and KCNB2 could not be knocked down at the single-cell level to investigate the changes of IKs, and AERP in atrial cells because of the low cell viability after viral infection and the lack of the specific KCNE1 and KCNB2 inhibitors in rabbits." (PMID 24386485, 2013).
cancer (3 papers, 2020 to 2026). A tumor composed of atypical neoplastic, often pleomorphic cells that invade other tissues. "Recurrent insertions were located near cancer-associated genes, including RB1, NEDD4, FTO, LAMA2, NOD1, and KCNB2, implicating LINE-1 activity in cis-regulatory remodeling of oncogenic pathways." (PMID 41681929, 2026).
tumor (2 papers, 2023 to 2025). "KCNB2 is previously found to be enriched in MB-propagating cells that contribute to drug resistance and tumor relapse; and loss of the KCNB2 channel can deplete this population in part through increased differentiation." (PMID 40150732, 2025). "Specifically, potassium channels such as Kv10.2 (EAG2), Kv2.2 (KCNB2), Kv1.5 (KCNA5), and Kir2.1 (KCNJ2) were upregulated in the MB tumor tissues and primary cultures." (PMID 40150732, 2025). "The eight probes extracted from the RFECV method showing discriminative power between tumour and nontumour samples included cg17105014 (GYPC), cg23273897 (MME), cg22083047 (PRICKLE2), cg09396217 (ANGPT1), cg01049530 (BMP3), cg18237405 (CPNE5), cg12741420 (IRF4) and cg11754206 (KCNB2)." (PMID 36779430, 2023).
infection (1 paper, 2013). The state of being infected such as from the introduction of a foreign agent such as serum, vaccine, antigenic substance or organism. "The expression levels of KCNE1 and KCNB2 were further downregulated (mRNA: to approximately 45% and 37% of the pacing group, respectively) by miR-1 overexpression via in vivo infection." (PMID 24386485, 2013). "However, AMO-1 infection reversed the A-TP-induced upregulation of miRNA-1 to approximately 49% of the pacing group, and recovered the expression levels of KCNE1 and KCNB2 (mRNA: to approximately 1.2-fold and 1.7-fold of the pacing group, respectively)." (PMID 24386485, 2013).
psychiatric disorder (1 paper, 2018). A disorder characterized by behavioral and/or psychological abnormalities, often accompanied by physical symptoms. "Although not segregating closely with BD, we identified CNVs affecting intronic regions of candidate genes previously implicated in psychiatric disorders (i.e., NLGN1, CNTNAP2, KCNB2 and CNTN5), each in different families." (PMID 29531218, 2018).
KCNB2 also shares sentences with these, for which no sentence is quoted: amyotrophic lateral sclerosis (1 paper); autism (1); brain tumor (1); cardiovascular disease (1); childhood asthma (1); gastric cancer (1); Neurodevelopmental delay (1); neurodevelopmental disorder (1); rectal cancer (1); rectum tumors (1); rheumatoid arthritis (1); sporadic amyotrophic lateral sclerosis (1); systemic lupus erythematosus (1).